INS (insulin)
Diseases named in the same sentence as INS in open-access papers (continued):
Sharing a sentence is not in itself a finding about the gene and the disease.
gestational diabetes (continued). "Economic reports give accurate cost estimation of different services given to diabetic patients, such as the annual insulin cost per patient for type 1, type 2, and gestational diabetes, which are 1155 SR (US $308), 1406 SR (US $375), and 1002 SR (US $267), respectively." (PMID 24025198, 2013). "Gestational diabetes is related to resistance and increasing insulin during pregnancy." (PMID 25243003, 2012). "This change towards a lower glycemic index diet could improve mother’s glucose tolerance below gestational diabetes level as well as lower mother’s insulin levels." (PMID 22568871, 2012). "Based on these findings, a hypothesis was proposed that use of a rapid-acting insulin analogue, insulin aspart (IAsp), may improve postprandial glycaemia during pregnancy complicated by gestational diabetes." (PMID 17888133, 2007). "We performed a cost-consequence analysis of treating women with mild gestational diabetes mellitus by dietary advice, blood glucose monitoring and insulin therapy as needed compared with routine pregnancy care, using patient-level data from a multi-centre randomised clinical trial." (PMID 17963528, 2007). "Treatment of women with gestational diabetes by dietary advice, blood glucose monitoring and insulin therapy as needed resulted in a reduction in serious perinatal complications, although more women experienced an induction of labour, and more of their infants were admitted to the neonatal nursery." (PMID 17963528, 2007). "Women between 24 and 34 weeks' gestation who had mild gestational diabetes were randomly assigned to receive dietary advice, blood glucose monitoring, and insulin therapy as needed (Intervention Group) or routine care according to standard practice at each centre." (PMID 17963528, 2007). "Gestational diabetes mellitus (GDM) is characterized by hyperglycemia-induced ROS generation, mitochondrial dysfunction, and impaired insulin signaling within placental and maternal tissues." (PMID 41614945, 2026). "These indicators may suggest a heightened risk of neonatal high levels of insulin, even in the absence of a maternal diagnosis of gestational diabetes." (PMID 40920364, 2026). "Gestational diabetes mellitus (GDM) is a multifactorial metabolic disorder arising from impaired insulin sensitivity and altered maternal–fetal energy regulation." (PMID 41516185, 2025). "Patients with gestational diabetes mellitus (GDM) should receive face-to-face insulin counselling at their first visit." (PMID 40950999, 2025). "Gestational Diabetes Mellitus (GDM) is one of the most common pregnancy complication characterized by hyperglycemia, primarily due to insulin resistance and inadequate pancreatic β-cell secretion." (PMID 40225328, 2025). "However, when the insulin levels fail to meet the requirements, gestational diabetes mellitus (GDM) may develop." (PMID 41470220, 2025). "The results showed that in women with gestational diabetes, there was a strong correlation between the appreciation of 10% sucrose-flavored milk and the level of fasting serum leptin, as well as a strong correlation between the average sweet taste of sweet solutions and fasting serum insulin level." (PMID 40806099, 2025). "The third trial on gestational diabetes compared the efficacy of metformin versus insulin for the treatment of GDM." (PMID 39889198, 2025). "Gestational diabetes mellitus (GDM) occurs during pregnancy due to inadequate insulin secretion or resistance." (PMID 39982365, 2025). "Gestational diabetes mellitus (GDM) is a condition characterized by hyperglycemia that develops during pregnancy, primarily due to insufficient β-cell insulin production and chronic insulin resistance." (PMID 40369565, 2025). "Gestational diabetes mellitus (GDM) is defined as gestational hyperglycemia as a result of an insufficient insulin response diagnosed during pregnancy." (PMID 40141785, 2025).
gestational diabetes (continued). "Gestational diabetes mellitus (GDM) is one of the most common disorders of pregnancy, affecting around 14% of pregnancies, globally, and occurs when there is an imbalance in insulin sensitivity and secretion." (PMID 39800861, 2025). "Vitamin D can regulate the course of gestational diabetes, which may be related to regulation of insulin gene transcription, insulin secretion, intracellular and cytosolic calcium balance, inhibition of oxidative stress and inflammatory responses and alteration of glucose metabolism." (PMID 39963668, 2025). "The observation that an inhibition by L-NAME was only detectable in the control group and the diabetic-treated gestational diabetes group might indicate a lower nitric oxide-mediated component of endothelium-dependent relaxation in the vessels of insulin-treated gestational diabetic mothers." (PMID 39384641, 2025). "GDM—Gestational Diabetes Mellitus arises when the body struggles to produce sufficient insulin to counteract the insulin resistance induced by placental hormones such as estrogen, cortisol, and human placental lactogen." (PMID 39057094, 2024). "The conventional care of gestational diabetes mellitus (GDM) mainly consists of regulating the diet, monitoring blood glucose levels, and administering insulin therapy." (PMID 39219840, 2024). "Gestational diabetes mellitus (GDM) is characterized by increased secretion of diabetogenic hormones from the placenta and an inadequate response of the pancreas to insulin resistance." (PMID 39356958, 2024). "Comparison of FBG, RBG, and Insulin levels in pregnant women with gestational diabetes mellitus (GDM) according to age of the patients." (PMID 39035597, 2024). "Mothers with gestational diabetes treated with dietary intervention (GDM G1) had similar milk composition to the mothers with insulin-treated gestational diabetes (GDM G2)." (PMID 39408278, 2024). "Gestational diabetes mellitus (GDM) arises when a pregnant woman's pancreatic function cannot meet the growing insulin demands." (PMID 39035682, 2024). "We compared cognitive profile and neuropsychological performance in 9-year-old offspring of mothers who were treated with metformin or insulin for gestational diabetes mellitus (GDM)." (PMID 38019468, 2023). "Therefore, VD3 supplementation during the antenatal period could prevent the development of gestational diabetes via its effects on insulin secretion, insulin sensitivity, body mass index (BMI), and adiponectin production." (PMID 37719527, 2023). "In addition, this state of surge in inflammatory cytokines is also responsible for the release of certain proteins and interleukins which inhibit the insulin signaling pathways, interfering with the insulin release and leading to potentially elevated blood sugar levels and gestational diabetes." (PMID 37492328, 2023). "Thus, vitamin D concentration may be important in the onset of gestational diabetes through conditioning pancreatic beta-cell function, modulation of insulin sensitivity, and inflammatory status." (PMID 37371857, 2023). "Since the Metformin in Gestational diabetes (MiG) trial, metformin, another pharmaceutical agent, has been increasingly recommended as an alternative or supplement to insulin in GDM treatment." (PMID 37597238, 2023). "So far, there have been no studies on whether gestational diabetes mellitus (GDM) - a common pregnancy complication that has been associated with impaired fetal insulin sensitivity but enhanced fetal growth, may affect cord blood myostatin concentration." (PMID 36875483, 2023). "A total of seven participants were diagnosed with gestational diabetes mellitus (GDM) during the study period, 2 of whom were treated with insulin." (PMID 37811749, 2023). "Compared to mothers with GDM, mothers who had pregestational diabetes had higher blood glucose concentrations and a higher proportion used insulin as treatment." (PMID 37029435, 2023).
gestational diabetes (continued). "The aim of this study was to elucidate the effect of metformin on oxidative stress and intestinal permeability in women with gestational diabetes mellitus (GDM) treated with metformin compared to those treated with insulin and healthy controls." (PMID 38001834, 2023). "A2 gestational diabetes mellitus (A2GDM) is a more severe form of GDM that requires additional medical intervention, such as insulin or oral antidiabetic drug (OAD)." (PMID 37680834, 2023). "The metabolic advantages of exercise during gestational diabetes (GDM) are believed to stem from changes affecting pathways that influence insulin sensitivity, adipokines, and reduction–oxidation reactions." (PMID 37763706, 2023). "In some cases, the excessive decline in insulin sensitivity can lead to a range of complications for both the mother and the baby, including gestational diabetes mellitus (GDM), pre-eclampsia, preterm birth, and large-for-gestational-age infants." (PMID 37299395, 2023). "[Note: females who lack pancreatic beta-cell plasticity and cannot increase insulin production to meet the demands of pregnancy develop gestational diabetes mellitus (GDM)]." (PMID 37110203, 2023). "In this contest, the metformin in gestational diabetes (MiG) trial prospectively compared pregnancy outcomes in more than 700 women with GDM randomized to either metformin (n = 363) or insulin treatment (n = 370)." (PMID 37401946, 2023). "The third, gestational diabetes (GDM), occurs when the body cannot produce enough insulin or develops a glucose intolerance during pregnancy and, when not properly managed, it can evolve into a lifelong condition of T2DM." (PMID 36677212, 2023). "Although the mainstay of drug therapy for gestational diabetes (GDM) is insulin, MTF is used in pregnancy with increasing frequency, though it is still limited to a maximum of 5–6% of all medications for GDM, depending on the country in which it is assessed." (PMID 35334606, 2022). "Women were categorised according to BMI and DM status [pre-gestational (P-DM; n = 59), insulin managed (I-GDM; n = 132) and diet managed gestational diabetes (D-GDM; n = 29)]." (PMID 35639703, 2022). "Gestational diabetes mellitus (GDM) develops when the maternal insulin secretion is insufficient to meet increased insulin demand during pregnancy." (PMID 36085031, 2022). "Gestational diabetes mellitus (GDM) patients have lower plasma oxytocin levels than healthy pregnant women, and oxytocin antagonists can impair insulin secretion and lead to the development of GDM symptoms in pregnant mice." (PMID 35669692, 2022). "Gestational diabetes mellitus (GDM) is a condition seen in pregnant women occur-ring when a buildup of glucose in the blood prevents insulin from being used effectively, affecting the fetus." (PMID 35954830, 2022). "In Gestational Diabetes Mellitus (GDM) the pregnancy-related physiological impairment of glycaemic control and insulin resistance are such that the mother, and consequently the fetus, are exposed to glycaemic levels considered diagnostic of diabetes." (PMID 34635186, 2021). "Of note, insulin therapy was also introduced in the US groups when maternal blood glucose values exceeded safety levels, 6.7 mmol/L (120 mg/dl) fasting or 11.1 mmol/L (200 mg/dl) post-meal, i.e., much above the usually recommended targets in women with gestational diabetes." (PMID 35069449, 2021). "Some prenatal exposures, such as maternal antenatal depression or insulin-treated gestational diabetes mellitus in a previous pregnancy, have been associated with negative gestational age acceleration, whereas others, such as maternal age and BMI, have been associated with positive age acceleration." (PMID 33926538, 2021).
gestational diabetes (continued). "Thus, several randomized trials were performed in women with gestational diabetes, comparing the initiation of insulin therapy based on maternal blood glucose values, or on an accelerated fetal growth, defined by an abdominal circumference (AC) ≥ 70th-75th percentile on US." (PMID 35069449, 2021). "Patients with gestational diabetes mellitus (GDM) have been traditionally recommended a diet and insulin when required." (PMID 34684418, 2021). "The deregulation of insulin status and the concomitant high glucose level in blood lead to a pathological condition named Gestational Diabetes Mellitus (GDM)." (PMID 34445135, 2021). "Although insulin is the first choice when it comes to treating pregnant women with gestational diabetes mellitus (GDM), metformin has also been debated as a good choice after modification of diet." (PMID 34804675, 2021). "This may be of particular importance with regards to populations at an increased risk of urinary tract infections, including diabetics, individuals with gestational diabetes, and those with severe trauma, all of whom exhibit an increased secretion of insulin in the urine." (PMID 34827287, 2021). "Myo-inositol (Myo) improves insulin resistance, glucose metabolism, and helps gestational diabetes (GDM) management." (PMID 34199095, 2021). "These conditions include gestational diabetes mellitus (GDM) and neural tube defects (NTDs), which arise from insulin resistance and altered cellular motility phenomena, respectively." (PMID 34070701, 2021). "Additionally, exposure to a negative pregnancy environment associated with insulin-treated gestational diabetes or maternal Sjögren’s syndrome have been linked to epigenetic age deceleration in umbilical cord blood." (PMID 34941772, 2021). "Notably, miR-33a-5p significantly inhibited cell growth and insulin production of pancreatic β-cells in gestational diabetes mellitus, which might imply a correlation between miR-33a-5p and the pathogenesis of PDAC." (PMID 34090323, 2021). "In the whole group (where important risk factors for adverse pregnancy outcomes have been excluded), 15 (2.7%) cases of preeclampsia (PE) and 20 (3.6%) cases of gestational diabetes mellitus with insulin therapy (GDM-2) were found." (PMID 32316207, 2020). "Gestational diabetes mellitus (GDM) is a common pregnancy complication characterized by decreased insulin sensitivity and inadequate insulin response." (PMID 32240241, 2020). "If these adaptions are insufficient and the insulin supply fail to match tissue demand, pregnant women develop gestational diabetes mellitus (GDM)." (PMID 32708966, 2020). "Gestational diabetes mellitus (GDM) is a condition of pregnancy resulting from insulin insensitivity." (PMID 32999269, 2020). "In pregnancies complicated by gestational diabetes mellitus (GDM), low GI diets reduced the amount of insulin required to maintain optimal glycaemic control." (PMID 30791647, 2019). "The authors concluded that high amounts of supplemented vitamin D increased insulin responsiveness and lowered insulin levels in women with gestational diabetes which could be beneficial in lowering maternal and neonatal complications related to gestational diabetes." (PMID 29976852, 2018). "Gestational diabetes mellitus (GDM) is a glucose intolerance disorder which occurs during pregnancy as a result of insulin insensitivity; it usually disappears after delivery." (PMID 29435415, 2018). "Placental studies have mostly assessed preselected, single miRNAs, such as miR-143, which was down-regulated in insulin-treated but not in diet-treated gestational diabetes and was associated with an altered metabolic switch between oxidative phosphorylation and aerobic glycolysis." (PMID 30424584, 2018). "During pregnancy, women can develop gestational diabetes mellitus (GDM) as a result of insulin insensitivity, but this usually disappears after delivery." (PMID 29435415, 2018).
gestational diabetes (continued). "Avery and Walker (2001) evaluated the effect of a single session cycling of 30 minutes duration on blood glucose and insulin level in population with gestational diabetes mellitus (GDM) of age ranged 18-38." (PMID 28811774, 2017). "Gestational diabetes mellitus (GDM) occurs when the pancreatic β-cells are unable to produce sufficient insulin to offset the persisting insulin resistance in pregnant women." (PMID 28732072, 2017). "In this study, 751 women with gestational diabetes (GDM) were randomised to either metformin or usual treatment with insulin therapy." (PMID 28770325, 2017). "By restricting analysis to deliveries after 37 weeks and excluding cases of undiagnosed pregestational diabetes, we identified a moderate increase in perinatal mortality in non-insulin-treated women with GDM." (PMID 28197657, 2017). "The aim of this meta-analysis was to determine the efficacy and safety of glyburide as a treatment for gestational diabetes mellitus (GDM) compared to insulin." (PMID 28771572, 2017). "Studies in women with gestational diabetes have shown compositional changes in the phospholipid bilayers when compared to controls, with proposed effects on receptor interactions that could alter the degree of insulin sensitivity in this population." (PMID 28574453, 2017). "Moreover, observed improvement after insulin treatment opens the door to therapeutic alternatives for children who are exposed to poorly controlled gestational diabetes, and who may benefit from more individualized treatments." (PMID 28768549, 2017). "Gestational IGT is considered to reflect a serious defect in beta-cell function in the early and late-phases of insulin secretion and is regarded as a sign of pre-gestational diabetes mellitus (GDM)." (PMID 27087160, 2016). "In addition, a prolongation of pregnancy could increase the exposure of the fetus to higher levels of glucose, insulin and different metabolic alterations if gestational diabetes is present." (PMID 27557930, 2016). "Gestational diabetes mellitus (GDM) is a state of glucose intolerance occurring during pregnancy and is related to both resistance to peripheral action of insulin and impairment of beta-cell function." (PMID 26057782, 2015). "The aim of this study was to evaluate the secular trends of incidence of gestational diabetes mellitus (GDM) and insulin treatment for GDM in a Korean population and to determine the factors that contribute to the trends in the incidence of GDM." (PMID 26292282, 2015). "The aim of this study was to determine the effect of gestational diabetes mellitus (GDM) on fetal insulin resistance or β-cell function in Chinese pregnant women with GDM." (PMID 23560057, 2013). "We recently demonstrated that osteocalcin is increased in women with gestational diabetes (GDM) compared to healthy pregnant women and related to enhanced insulin secretion." (PMID 22844418, 2012). "Management for women with gestational diabetes mellitus (GDM) consists of dietary counselling and physical exercise, and for those women who fail to maintain glycemic goals, insulin therapy." (PMID 21429234, 2011). "Gestational diabetes mellitus (GDM) is a condition during pregnancy characterized by abnormally high maternal blood glucose due to insulin resistance and/or insufficient insulin secretion." (PMID 40290026, 2025). "These processes may mediate the pathogenesis of gestational diabetes mellitus (GDM) by disrupting insulin signaling pathways." (PMID 41304535, 2025). "Among the 36 women diagnosed with gestational diabetes mellitus (GDM) in this study, 16 were managed through dietary intervention and 20 required insulin therapy." (PMID 40369565, 2025). "It is worth noting that we had the data on maternal gestational diabetes mellitus (GDM) and whether they had started using insulin during the index pregnancy." (PMID 39934344, 2025).